KDM5A (lysine demethylase 5A)
Description:
Histone demethylase that specifically demethylates 'Lys-4' of histone H3, thereby playing a central role in histone code. Does not demethylate histone H3 'Lys-9', H3 'Lys-27', H3 'Lys-36', H3 'Lys-79' or H4 'Lys-20'. Demethylates trimethylated and dimethylated but not monomethylated H3 'Lys-4'. Regulates specific gene transcription through DNA-binding on 5'-CCGCCC-3' motif. May stimulate transcription mediated by nuclear receptors. Involved in transcriptional regulation of Hox proteins during cell differentiation. May participate in transcriptional repression of cytokines such as CXCL12. Plays a role in the regulation of the circadian rhythm and in maintaining the normal periodicity of the circadian clock. In a histone demethylase-independent manner, acts as a coactivator of the CLOCK-BMAL1-mediated transcriptional activation of PER1/2 and other clock-controlled genes and increases histone acetylation at PER1/2 promoters by inhibiting the activity of HDAC1 (By similarity). Seems to act as a transcriptional corepressor for some genes such as MT1F and to favor the proliferation of cancer cells.
Synonyms: RBBP-2; RBBP2; RBP2; NEDEHC; formerly JARID1A
Tractability: Small molecule: a structure with a bound ligand is known; a high-quality ligand is known. PROTAC: UniProt records ubiquitination sites on it; ubiquitination databases record sites on it; its protein half-life has been measured; a small molecule that binds it is known.
Target class: Epigenetic regulator; Jumonji domain-containing; Eraser; Lysine demethylase
Gene: Protein-coding gene on chromosome 12 (280,057 to 389,320, reverse strand). Ensembl gene ENSG00000073614.
Subcellular location: Nucleus, nucleolus; Nucleus
Subcellular location (Human Protein Atlas): Nuclear bodies; Cytosol
Pathways (Reactome):
Chromatin organization: HDMs demethylate histones
Developmental Biology: Chromatin modifications during the maternal to zygotic transition (MZT)
Gene Ontology:
Molecular function: DNA binding; histone binding; histone H3K4me/H3K4me2/H3K4me3 demethylase activity; protein binding; transcription cis-regulatory region binding; zinc ion binding; enzyme inhibitor activity; histone demethylase activity; transcription coactivator activity; chromatin binding; chromatin DNA binding; histone H3K4 demethylase activity
Biological process: positive regulation of DNA-templated transcription; transcription initiation-coupled chromatin remodeling; circadian regulation of gene expression; regulation of DNA-templated transcription; epigenetic regulation of gene expression; facultative heterochromatin formation
Cellular component: nuclear body; nucleus; chromatin; nucleoplasm; nucleolus; protein-DNA complex
Genetic constraint (gnomAD): Loss-of-function variants: 36 observed, 175.75 expected, observed/expected ratio (o/e) 0.2, 90% interval 0.16 to 0.27. The upper end of that interval is the gene's LOEUF score, 0.27, which puts it in group 1 of 6, group 1 being the genes least tolerant of losing a copy. Missense variants: 1,555 observed, 1,996.7 expected, observed/expected ratio (o/e) 0.78, 90% interval 0.75 to 0.81. Synonymous variants: 742 observed, 704.89 expected, observed/expected ratio (o/e) 1.05, 90% interval 0.99 to 1.12.
Gene-disease validity (ClinGen):
ClinGen rates the evidence that KDM5A causes each of these diseases.
congenital heart disease (autosomal dominant): Limited. A heart disease that is present at birth.
Homologues: Orthologues: chimpanzee KDM5A (99% identical), macaque KDM5A (99% identical), dog KDM5A (98% identical), pig KDM5A (98% identical), rabbit KDM5A (98% identical), mouse Kdm5a (97% identical), rat Kdm5a (97% identical), guinea pig KDM5A (84% identical), tropical clawed frog kdm5a (81% identical), zebrafish KDM5A (52% identical), Drosophila melanogaster Kdm5 (40% identical), Caenorhabditis elegans rbr-2 (26% identical). Paralogues in human: KDM5C (49% identical), KDM5B (48% identical), KDM5D (47% identical), KDM4B (13% identical), KDM4A (12% identical), KDM4C (12% identical), JARID2 (12% identical), KDM4D (8% identical), KDM4F (8% identical), KDM4E (7% identical).
Diseases named in the same sentence as KDM5A in open-access papers:
KDM5A is named in the same sentence as 111 diseases in open-access papers, as found by Europe PMC text mining. Sharing a sentence is not in itself a finding about the gene and the disease. The quoted sentences say what the papers report.
breast cancer (33 papers, 2013 to 2024). A primary or metastatic malignant neoplasm involving the breast. "The results showed that most of the patients with KDM5A gene mutation had a family history of breast cancer and melanoma or a pathological pancreatic cancer subtype of pancreatic mucinous adenocarcinoma." (PMID 35493099, 2022). "It has been shown that there is a strong association between KDM5A expression in breast cancer and drug tolerance." (PMID 34073849, 2021). "In PIK3CAH1047R-mutated breast cancer, the phosphorylation of KDM5A by the overactivated AKT blocks its translocation to the nucleus, which limits the access of KDM5A to its substrates, H3K4me2 and H3K4me3." (PMID 33664847, 2021). "In the MMTV-Neu breast cancer mouse model, loss of KDM5A slowed tumorigenesis as well as metastasis to the lungs." (PMID 27224921, 2016). "In summary, the frequency of KDM5A/B/C gene mutations was higher in patients with pancreatic cancer, while patients with a history of drinking, a family history of breast cancer, and a family history of melanoma or a history of chronic pancreatitis were more likely to develop KDM5A/B/C mutations." (PMID 35493099, 2022). "KDM5A is mutated in acute myeloid leukemia and plays a role in breast cancer formation." (PMID 32531926, 2020). "Furthermore, KDM5A expression is implicated in drug resistance to targeted anti-cancer therapies in both lung and breast cancer, as well as in resistance to a DNA alkylating agent in glioblastoma." (PMID 27224921, 2016). "That study revealed that FBXO22 expression was lower in TNBC cells than in cells of other breast cancer subtypes and, conversely, that the KDM5A protein level was increased in TNBC cells." (PMID 39394462, 2024). "KDM5A drives a range of human cancers including acute myeloid leukemia, glioblastoma, renal cell carcinoma, and prostate, lung, gastric, and breast cancers." (PMID 38769556, 2024). "Compound 1 promotes the accumulation of p16 and p27 by inhibiting KDM5A-mediated H3K4me3 demethylation, leading to cell cycle arrest and the senescence of breast cancer cell lines." (PMID 36975603, 2023). "Shows efficacy against several KDM5A-overexpressing breast cancer cell lines such as MDA-MB-231, MCF-7, and MCF-10A." (PMID 36975603, 2023). "Immunoblotting results confirmed that KDM5A was lowly expressed in luminal-type breast cancer cells MCF-7, T47D, and ZR-75–1 compared to MCF-10A cells." (PMID 36112263, 2023). "Patients with a family history of breast cancer and melanoma, history of drinking or history chronic pancreatitis were more likely to have KDM5A/B/C gene abnormalities, which were related to a variety of adverse clinical features." (PMID 35493099, 2022). "Studies have shown that KDM5A promotes the resistance of breast cancer cells to clinical drugs such as trastuzumab and erlotinib by blocking the regulation of p21 and BCL2-antagonist/killer 1 (Bak1)." (PMID 35493099, 2022). "KDM5A is closely related to breast cancer, prostate cancer, ovarian cancer and small-cell lung cancer." (PMID 35493099, 2022). "In estrogen receptor (ER)-positive breast cancer, KDM5A is key regulator of phenotypic heterogeneity and inhibition of the enzyme activity increases sensitivity to endocrine therapy." (PMID 33436536, 2021). "An elective KDM5A (a histone demethylase) inhibitor has been reported to induce senescence and repress the proliferation of KDM5A-overexpressing breast cancer cell lines." (PMID 34458273, 2021). "Mechanistically, this KDM5A inhibitor induces G1 cell cycle arrest of breast cancer cell and cellular senescence by up-regulation of p16 and p27." (PMID 34458273, 2021). "KDM5A is frequently overexpressed in primary breast cancer cases and increase the proliferation, metastasis, and drug resistance of breast cancer." (PMID 33596982, 2021). "KDM5A gene is significantly amplified and overexpressed in various human cancers, such as ovarian cancer, small cell lung cancer and breast cancer." (PMID 33087165, 2020).
breast cancer (continued). "Dysregulation of KDM5A is involved in the pathomechanism of various human malignant diseases, such as breast cancer and acute myeloid leukemia." (PMID 32531926, 2020). "Previous studies have shown that KDM5A increased breast cancer cell proliferation, while knockdown of KDM5A altered H3K4 methylation and induced apoptotic cell death." (PMID 30650517, 2019). "MDA-MB-231, MDA-MB-468, and MCF-7 cells are KDM5A-overexpressing breast cancer cell lines, while the breast cancer cell line MCF-10A and the normal liver cell line LO2 express relatively low levels of KDM5A." (PMID 30650517, 2019). "This in turn induced cell cycle arrest in the G1 phase and cell senescence of KDM5A-overexpressing breast cancer cells." (PMID 30650517, 2019). "In breast cancer tissues, cells with KDM5A gene amplification were found to be more resistant to erlotinib, an inhibitor of the tyrosine kinase epidermal growth factor receptor (EGFR), when compared to cells without the same amplification." (PMID 35582714, 2019). "KDM5A, a histone demethylase, can increase the proliferation, metastasis, and drug resistance of cancers, including breast cancer, and is thus an important therapeutic target." (PMID 30650517, 2019). "The authors reported that breast cancer cells with KDM5A gene amplification and hence, with up-regulated KDM5A mRNA and protein levels, were found to be more tolerant to the EGF receptor TKI erlotinib when compared to cells without the same amplification." (PMID 35582714, 2019). "The data revealed that compound 1 have much higher cytotoxicity than 18 in four breast cancer cell lines and KDM5A inhibitors selectively inhibit breast cancer cell lines." (PMID 30650517, 2019). "It was reported that KDM5A is required to develop a metastable chromatin state that enables drug resistance in breast cancer and lung cancer treated with EGFR-TKI." (PMID 31448219, 2019). "Taken together, these results highlight the potential of 1 to be used as a structural motif for developing KDM5A chemical probes and/or clinical inhibitors particularly against KDM5A-overexpressing breast cancer." (PMID 30650517, 2019). "Histone H3 lysine 4 demethylase KDM5A is critical for breast cancer progression and metastasis by facilitating the expression TNC and other genes, but the mechanism is independent of the demethylase activity of KDM5A." (PMID 27756687, 2017). "These experiments provide the first evidence that the demethylase activity of KDM5A is necessary for both lung and breast cancer cells to develop resistance to targeted therapies." (PMID 27224921, 2016). "In order to further validate the cellular function of YUKA1, we tested YUKA1 in ZR-75-1 breast cancer cells, a cell line with KDM5A amplification and in which RNAi-mediated knockdown of KDM5A resulted in decreased cell proliferation." (PMID 27224921, 2016). "In addition, lysine demethylase 5 A (KDM5A) increases resistance to multiple anticancer drugs, including breast cancer resistance to erlotinib and lung cancer cell resistance to gefitinib, by removing histone methylation." (PMID 39424627, 2024). "KDM5A degradation has also been investigated in the context of breast cancer." (PMID 39394462, 2024). "Partly in line with our results, the cyclopenta[c]chromen derivative 1 (an identified antagonist of KDM5A) is capable of inducing production of p16 and p27 via blockage of KDM5A-mediated H3K4me3 demethylation, resulting in cell cycle arrest and senescence in breast cancer." (PMID 36112263, 2023). "A growing pool of literature demonstrates that KDM5A is highly expressed in various cancer tissues, including gastric cancer, acute myeloid leukemia, and breast cancer, and proves that KDM5A is a potential molecular biomarker and novel target for cancer therapy." (PMID 36396833, 2022). "Additionally, compound 1 repressed the proliferation of various KDM5A-overexpressing breast cancer cell lines." (PMID 30650517, 2019).
breast cancer (continued). "KDM5A is upregulated in a variety of breast cancer cell lines." (PMID 30650517, 2019). "In addition, our research provides a possible anti-cancer mechanism of KDM5A inhibitors and highlights the feasibility and significance of KDM5A as a therapeutic target for KDM5A-overexpressing breast cancer." (PMID 30650517, 2019). "Similarly, KDM5A knock-down in medulloblastoma and breast cancer suppressed cell proliferation with the induction of apoptotic genes expression." (PMID 31160694, 2019). "Moreover, compound 1 caused growth arrest, and induced cell senescence of breast cancer cells, rendering it as a potential lead compound for the development of more efficacious drug candidates against KDM5A-overexpressing breast cancer." (PMID 30650517, 2019). "Additionally, compound 1 also reduced the growth of various breast cancer cell lines, possibly through inhibition of the KDM5A–H3K4me3 interaction and induction of G1 phase cell cycle arrest together with cell senescence." (PMID 30650517, 2019). "Therefore, the development of potent and selective KDM5A inhibitors for treating breast cancer is urgently needed." (PMID 30650517, 2019). "However, KDM5A was recently shown to promote breast cancer progression and metastasis in a demethylase-independent manner." (PMID 25329053, 2014). "Therefore, we speculated that in breast cancer, Fbxo22 may degrade KDM5A protein by ubiquitination." (PMID 36112263, 2023). "KDM5A and KDM5B, which are commonly overexpressed in luminal breast cancer, modulate ER signaling, alter gene expression profiles, and promote endocrine therapy resistance." (PMID 35453496, 2022). "This is similar to investigations of the pro-metastatic role of KDM5A in breast cancer, where KDM5A was found to upregulate expression of TNC (also identified as a KDM5A-dependent gene in our studies) via a demethylase-independent mechanism." (PMID 33196691, 2020). "Moreover, our cytotoxicity assay results indicated that compound 1 could repress the growth of KDM5A-overexpressing breast cancer cell lines, with subsequent KD5MA knockdown experiments demonstrating that the anti-proliferative effect of 1 likely results from its inhibitory activity against KDM5A." (PMID 30650517, 2019). "YUKA1 and YUKA2 were tested for their abilities to inhibit KDM5A in vivo using HeLa cervical cancer and MCF7 breast cancer cell lines." (PMID 27224921, 2016). "However, high expression of KDM5A was observed in TNBC cells MDA-MB-231, MDA-MB-468, and Hs578T compared to luminal type breast cancer cells." (PMID 36112263, 2023). "KDM5A is responsible for the proliferation and drug tolerance of HER2-positive breast cancer." (PMID 33596982, 2021). "As KDM5A was shown to mediate drug tolerance, we investigated the ability of YUKA1 to prevent drug tolerance in EGFR-mutant lung cancer cells treated with gefitinib and HER2+ breast cancer cells treated with trastuzumab." (PMID 27224921, 2016). "Consistent with previous data from our laboratory and others that KDM5A-dependent cells require its demethylase activity for cell proliferation, YUKA1 inhibited proliferation of HeLa cervical cancer cells and ZR-75-1 breast cancer cells." (PMID 27224921, 2016). "screened and identified a 3-thio-1,2,4-triazole derivative YUKA1 as a KDM5A inhibitor with an in vitro IC50 value of 2.66 ± 0.69 μM, this compound reduced gefitinib- and trastuzumab-induced drug tolerance in EGFR-mutant lung cancer cells and HER2 + breast cancer cells, respectively." (PMID 33596982, 2021). "KDM5A promotes drug resistance of clinical drugs such as trastuzumab and erlotinib via deregulating p21 and BCL2-antagonist/killer 1 (Bak1), and facilitates the proliferation of many HER2-positive breast cancer cell lines through mediating cell cycle and apoptosis." (PMID 33596982, 2021).
lung carcinoma (19 papers, 2011 to 2025). "KDM5A promotes cell cycle progression by repressing p27 and activating cyclins D1 and E1 in lung cancer cells." (PMID 33578894, 2021). "KDM5A is overexpressed in lung cancer tissues and facilitates cell proliferation, invasion, and metastasis of lung cancer via inhibiting the expression of p27 and upregulating cyclin D1, and ITGB1." (PMID 33596982, 2021). "In lung cancer cells, KDM5A binds directly to the promoter regions of cyclin D1 and cyclin-dependent kinase inhibitor p27 (KIP1) and promotes G1-S progression by activating cyclins D1 and E1 and suppressing p27 (CDKN1B)." (PMID 33578894, 2021). "Thus, the authors provided the first evidence that the demethylase activity of KDM5A is involved in gefitinib resistance in lung cancer cells." (PMID 35582714, 2019). "KDM5A, a H3K4-spesific KDM demethylase, was found to be implicated in developing drug resistance in a study on the epigenetic basis of cancer drug resistance, and it was enriched in lung cancer tissues as well as drug-resistant cells." (PMID 30002791, 2018). "Similarly, KDM5A was found to be important for epithelial-mesenchymal transition and invasion of lung cancer cells." (PMID 27224921, 2016). "Consistent with deregulation of KDM5A in leukemia, this gene was prevalently expressed in cluster 1, and the KDM5A overexpression seen in lung cancer cell lines may be due to their CD133-positive character." (PMID 21886846, 2011). "Thus, in lung cancer cells, metformin might increase p21 and p27 expression by upregulating H3K4me3 at the promoter region of each gene through the downregulation of KDM5A." (PMID 33578894, 2021). "For example, in EGFR‐mutant lung cancer, IGF‐1R signal transduction required for the DT state is regulated via KDM5A demethylation." (PMID 37638338, 2023). "Increased levels of KDM5A, KDM5B and FBXL10 have also been observed in hepatocellular carcinoma, gastric cancer, lung cancer, pancreatic ductal adenocarcinoma, bladder cancer, colorectal cancer and prostate cancer." (PMID 31160694, 2019). "KDM5A was also shown to mediate resistance to a second EGFR inhibitor called gefitinib, in EGFR-mutant lung cancer cell lines." (PMID 35582714, 2019). "In addition to this, KDM5A was also shown to mediate resistance to a second EGFR inhibitor, called gefitinib, in EGFR-mutant lung cancer cell lines." (PMID 35582714, 2019). "KDM5A was shown to be a powerful mediator of drug tolerance to gefitinib, a small molecule inhibitor of the epidermal growth factor receptor (EGFR), in the EGFR-mutant lung cancer cell line PC9." (PMID 27224921, 2016). "KDM5A, also known as retinoblastoma binding protein (RBP2), was initially identified as a binding partner of retinoblastoma protein, and its overexpression has been observed in cancers such as glioblastoma, gastric cancer, hepatocellular carcinoma, and lung cancer." (PMID 33578894, 2021). "Additionally, a selective inhibitor of KDM5A, YUKA1, suppressed cell proliferation and prevented drug resistance in various cancer cell lines including A549, implicating its application potential in lung cancer treatment." (PMID 30002791, 2018). "Likewise, the normal-like MCF10A cells and PC9 lung cancer cells were not affected by KDM5A knockdown or by treatment with YUKA1." (PMID 27224921, 2016).